THRIL (TNF and HNRNPL related immunoregulatory long non-coding RNA)
Diseases named in the same sentence as THRIL in open-access papers (continued):
Sharing a sentence is not in itself a finding about the gene and the disease.
Crohn disease (1 paper, 2022). A gastrointestinal disorder characterized by chronic inflammation involving all layers of the intestinal wall, noncaseating granulomas affecting the intestinal wall and regional lymph nodes, and transmural fibrosis. "Serum LncRNA THRIL and MiR-125b could be used as potential biomarkers for diagnosis and prognosis of ulcerative colitis and Crohn’s disease." (PMID 36206229, 2022).
influenza (1 paper, 2025). An acute viral infection of the respiratory tract, occurring in isolated cases, in epidemics, or in pandemics; it is caused by serologically different strains of viruses (influenzaviruses) designated A, B, and C, has a 3-day incubation period, and usually lasts for 3 to 10 days. "Understanding the precise mechanisms by which THRIL exerts its effects on interferon regulation could provide valuable insights into the pathogenesis of influenza and potentially uncover new targets for therapeutic intervention." (PMID 40006907, 2025).
Insulin resistance (1 paper, 2018). Increased resistance towards insulin, that is, diminished effectiveness of insulin in reducing blood glucose levels. "In contrast, expression levels of lncRNAs, viz., SALRNA1 and THRIL, were negatively correlated to glycemic control, insulin resistance, markers of senescence, inflammation, and HDAC3 and positively correlated to telomere length." (PMID 30139387, 2018).
leukopenia (1 paper, 2023). "Subsequently, we observed that the mRNA level of HOTAIR and THRIL genes exhibited no discernible correlation with the occurrence of clinical features, including fever, drug resistance, liver injury, lung infection, hypoproteinemia, leukopenia, and positive sputum smear in PTB patients." (PMID 38087305, 2023).
lung injury (1 paper, 2021). "Downregulation of THRIL prevented inflammatory responses, and apoptosis in septic-induced acute lung injury." (PMID 34956235, 2021).
lymphopenia (1 paper, 2016). Reduction in the number of lymphocytes. "In this regard the clinical protocol for ThRIL is based on a Treg supportive immunosuppressive regimen including the use anti-thymocyte globulin (ATG), to induce lymphopenia with a preferential preservation of Tregs." (PMID 26788992, 2016).
myocardial infarction (1 paper, 2023). Gross necrosis of the myocardium, as a result of interruption of the blood supply to the area, as in coronary thrombosis. "The combination of THRIL and miR-99a synergistically regulates the process of myocardial infarction." (PMID 37582734, 2023).
periodontitis (1 paper, 2020). An acute or chronic inflammatory process that affects the tissues that surround and support the teeth. "In the current study, we investigated the role of TNF and HNRNPL related immunoregulatory (THRIL) and p50-associated COX-2 extragenic RNA (PACER) lncRNAs in periodontitis." (PMID 32426538, 2020). "In the current study, we aimed at identification of the expression pattern of TNF and HNRNPL related immunoregulatory (THRIL) and p50-associated COX-2 extragenic RNA (PACER) lncRNAs in the periodontitis." (PMID 32426538, 2020). "Based on the role of TNF-α and COX-2 in the pathogenesis of periodontitis, THRIL and PACER are putative contributors in this inflammatory condition." (PMID 32426538, 2020). "The current investigation aimed at identification of the expression pattern of THRIL and PACER in blood and tissue samples of patients with periodontitis and healthy subjects." (PMID 32426538, 2020).
rheumatoid arthritis (1 paper, 2021). A chronic, systemic autoimmune disorder characterized by inflammation in the synovial membranes and articular surfaces. "The expression of THRIL is increased in T cells of patients with rheumatoid arthritis, and THRIL plays a key role in adaptive immune cell differentiation and functions." (PMID 33675584, 2021).
cancer (2 papers, 2023). A tumor composed of atypical neoplastic, often pleomorphic cells that invade other tissues. "This publication also emphasized that the level of THRIL in serum ascended in benign SPN and malignant SPN groups, indicating the connection between THRIL and SPN." (PMID 37582734, 2023).
infection (2 papers, 2025). The state of being infected such as from the introduction of a foreign agent such as serum, vaccine, antigenic substance or organism. "Validation through qRT-PCR confirmed a substantial decrease in THRIL expression correlating with extended infection durations, suggesting a consistent downregulatory effect across different viral strains." (PMID 40006907, 2025). "Subsequently, we infected A549 cells at various multiplicities of infection (MOIs) with the PR8 virus and assessed THRIL expression patterns via qRT-PCR at 12 h post-infection." (PMID 40006907, 2025). "Especially, several lncRNAs that exhibited transcriptional regulation, such as GAS5, THRIL, MIR155HG, and UCA1, also displayed consistent or increased m6A methylation signals following infection." (PMID 41267684, 2025). "NORAD, THRIL, and GAS5 are involved in regulation of the NF-κB signaling pathway, a central axis of immune activation in response to respiratory viral infections and showed increased expression in infection." (PMID 41267684, 2025).
immune diseases (1 paper, 2019). "There have been only a few studies revealing the aberrant expression and function of lnc‐THRIL in patients with inflammatory and auto‐immune diseases." (PMID 31257645, 2019).
tumor (1 paper, 2023). "In summary, the expression of THRIL was increased with the growth of SPN and in line with the increment of tumor markers, such as CEA, CA124, CYFRA21-1, and NSE." (PMID 37582734, 2023).
THRIL also shares sentences with these, for which no sentence is quoted: acute respiratory distress syndrome (2 papers); allergic rhinitis (1); autoimmune disease (1); bladder cancer (1); breast carcinoma (1); epilepsy (1); hepatocellular carcinoma (1); inflammatory bowel disease (1); liver cancer (1); lymphoma (1); malignant pleural mesothelioma (1); melanoma (1); multiple myeloma (1); neurological disorders (1); non-small cell lung carcinoma (1); oral cancer (1); pulmonary tuberculosis (1); stomach cancer (1); temporal lobe epilepsy (1); thyroid cancer (1); type 2 diabetes (1); ulcerative colitis (1).